REN (renin)
Diseases named in the same sentence as REN in open-access papers (continued):
Sharing a sentence is not in itself a finding about the gene and the disease.
hypertrophic cardiomyopathy (19 papers, 2017 to 2025). A condition in which the myocardium is hypertrophied without an obvious cause. "The analysis of bioinformatics suggested that the differentially abundant proteins were commonly associated with the renin-angiotensin system, vitamin digestion and absorption, hypertrophic cardiomyopathy, and so on." (PMID 37304842, 2023). "Additional enriched pathways included the intestinal immune network for IgA production, inflammatory bowel disease, renin secretion, thyroid hormone synthesis, pertussis, and hypertrophic cardiomyopathy." (PMID 39768386, 2024). "The differentially expressed genes (DEGs) were mainly categorized into those involved in the renin-angiotensin system, viral myocarditis, and hypertrophic cardiomyopathy." (PMID 36457307, 2022). "For downregulated DEGs, 36 significantly enriched pathways were obtained; the top three identified pathways were “viral myocarditis,” “renin-angiotensin system,” and “hypertrophic cardiomyopathy”." (PMID 36457307, 2022). "KEGG enrichment analysis showed that downregulated pathways were enriched in regulating lipolysis as well as Peroxisome proliferator activated receptor (PPAR) signaling pathways in adipocytes, and upregulated pathways were enriched in renin secretion and hypertrophic cardiomyopathy." (PMID 38716355, 2024). "In addition, interactions between viral proteins and cytokines, inflammatory diseases, diabetic complications, hypertrophic cardiomyopathy, the renin-angiotensin system, and other pathways were also identified in the enrichment analysis." (PMID 35165525, 2022).
IgA nephropathy (19 papers, 2011 to 2025). "In a randomized controlled clinical trial on 78 patients affected by IgA nephropathy, PUFAs associated with renin-angiotensin system blockers were more effective than renin-angiotensin system blockers alone in reducing proteinuria." (PMID 28698529, 2017). "The key management strategy for IgA nephropathy is blood pressure control with renin-angiotensin aldosterone blockade." (PMID 35430806, 2022). "Renin-angiotensin system inhibitors (RASi) are the first choice and basic therapy for the treatment of IgA nephropathy (IgAN) with proteinuria." (PMID 36091017, 2022). "Inhibitors of the renin-angiotensin system (RAS) are cornerstones of supportive therapy in patients with IgA nephropathy (IgAN)." (PMID 32856272, 2020). "Angiotensin converting enzyme inhibitor (ACEI) and angiotensin receptor blocker (ARB) as the commonly used renin-angiotensin aldosterone system inhibitor are widely used in patients with IgA nephropathy (IgAN), but the effect is controversy." (PMID 31700813, 2019). "The underlying mechanisms may include renin-angiotensin-aldosterone system activation, leptin, adiponectin, fetuin-A, and adipose tissue inflammation, as factors that contribute to glomerulonephritis, focal and segmental glomerulosclerosis, and IgA nephropathy." (PMID 26651346, 2015). "For example, in the case of renin vaccine, the autoimmune nephritis was induced by the observation of immune complex depositions same as Lupus nephritis or IgA nephropathy." (PMID 23544146, 2013). "Renin, another key node which is upstream of angiotensin in a number of known pathways, could play a role in IgA nephropathy progression by activation the intra-renal oxygen reactive species." (PMID 24339887, 2013). "What is more, one recent study reported that HCQ combined with renin–angiotensin–aldosterone system inhibitors can reduce the proteinuria of patients with IgA nephropathy without major adverse events." (PMID 39286239, 2024). "Here we present the case of a 39-year-old who got JGA hyperplasia of IgA nephropathy (IgAN) after long-term inhibition of the renin-angiotensin system (RAS) with an angiotensin receptor blocker (ARB), and a direct renin inhibitor (DRI) in combination with a diuretic." (PMID 28509110, 2015). "Tonsillectomy may improve renal survival rates in patients with IgA nephropathy independent of conventional therapy using renin-angiotensin system inhibitors and corticosteroids." (PMID 31150076, 2019).
systemic lupus erythematosus (19 papers, 2016 to 2024). An autoimmune multi-organ disease typically associated with vasculopathy and autoantibody production. "KEGG analysis showed that the molecules upregulated in patients with high DUSP7 levels were mainly enriched in transcriptional misregulation in cancer, systemic lupus erythematosus, salivary secretion, renin-angiotensin system, and relaxin signaling pathway." (PMID 37538139, 2023). "cSiO2 also elicited extracellular granzyme B, which has been linked to lupus pathogenesis by cleaving autoantigens and exposing neoepitopes, as well as ACE and the aspartic acid protease renin 1, two key enzymes in the renin-angiotensin system." (PMID 35126352, 2021). "Beyond empiric recommendations for renin‐angiotensin system inhibition, there is limited data to guide treatment of patients with either HIV‐associated lupus‐like glomerulonephritis, or HIVICK more broadly." (PMID 32983458, 2020). "Systemic lupus erythematosus and the renin-angiotensin system were identified as downregulated pathways." (PMID 26861288, 2016). "Interestingly, systemic lupus erythematosus, necroptosis, vascular smooth muscle contraction, and renin secretion pathways were found to be potentially related to PDNS induced by PCV3 infection." (PMID 34113334, 2021). "Pathways involved in ACTH-secreting tumors included drug metabolism enzymes, metabolism of xenobiotics by cytochrome P450, renin-angiotensin system, tryptophan and pyrimidine metabolism and those involved in immune related events such as in systemic lupus erythematosus." (PMID 33168897, 2020). "The Kyoto Encyclopedia of Genes and Genome (KEGG) pathway enrichment analysis revealed the altered proteins with their important signal pathway, including renin-angiotensin system, glycosaminoglycan biosynthesis pathway, PPAR signaling pathway, alcoholism, and systemic lupus erythematosu." (PMID 34413926, 2021). "The top ten significant pathways were as follows: systemic lupus erythematosus, spliceosomes, amoebiasis, African trypanosomiasis, porphyrin and chlorophyll metabolism, Amyotrophic lateral sclerosis (ALS), Malaria, Renin secretion, Taurine and hypotaurine metabolism, and Tuberculosis." (PMID 32509863, 2020).
adenoma (18 papers, 2010 to 2026). A neoplasm arising from the epithelium. "The patient was found to have an aldosterone-producing adenoma based on an elevated aldosterone-to-renin ratio and was started on a mineralocorticoid antagonist." (PMID 32923203, 2020). "Pathway enrichment analysis revealed specific alterations of these clusters: calcium signaling pathway in CNFPA; renin-angiotensin system for ACTH-adenomas and fatty acid metabolism for the TSH-, PRL-, GH-cluster." (PMID 33168897, 2020). "Aldosterone secretion is normally suppressed when renin is low, unless there is autonomous aldosterone production—eg, from an aldosterone-producing adenoma." (PMID 29655877, 2018). "The fact that her renin was low from the beginning implied that an autonomous source of aldosterone was keeping renin suppressed, which points to an adrenal aldosterone-producing adenoma or bilateral adrenal hyperplasia." (PMID 41356982, 2025). "Cortisol production from the adenoma may elevate PRA levels by increasing the renin substrate angiotensinogen while suppressing aldosterone secretion through the ACTH pathway." (PMID 35482752, 2022). "Pre-operative serum potassium, plasma aldosterone level, aldosterone to renin ratio, lateralization index at AVS, and adenoma size were similar between the two groups." (PMID 26807823, 2016).
blood pressure (18 papers, 2013 to 2025). "The high blood pressure caused by abnormalities in the renin–angiotensin system resulted in severe renal disorder in spontaneously hypertensive rats or SHRSP, indicating that the Can diet may affect the renin–angiotensin system and injure the kidneys, irrespective of changes to blood pressure." (PMID 34511125, 2021). "Later symptoms of fatigue and low blood pressure, combined with high potassium, suppressed aldosterone, and high renin, confirmed the diagnosis of immune checkpoint inhibitor-associated adrenalitis, while ACTH remained low due to pituitary function impairment." (PMID 40860571, 2025). "Oral antihypertensive drugs are widely used to manage high blood pressure, primarily by regulating the renin-angiotensin-aldosterone system." (PMID 38373214, 2024). "ACEI is the main high blood pressure drug for patients with renal hypertension (high renin/high aldosterone), while synthetic ACEIs are commonly associated with certain toxicity and side effects." (PMID 36235721, 2022). "Our previous study demonstrated that activation of the renin–angiotensin–aldosterone system, local shear stress on the plaque, and high blood pressure, can promote plaque rupture." (PMID 33679879, 2021). "As more cysts develop, the renin-angiotensin-aldosterone system (RAAS) is activated leading to high blood pressure very early in the pathogenesis." (PMID 31419965, 2019). "Vaccination against the renin-angiotensin system has been developed to lower high blood pressure." (PMID 29495280, 2018). "Finally, the mechanism for the reduction of high blood pressure likely includes modulation of the renin-angiotensin system." (PMID 23586038, 2013). "This hyper susceptibility is dependent on active renin and independent of high blood pressure." (PMID 27271344, 2016). "However, the subsequent physiological consequences are ignorable because this downregulation on the mRNA level was not accompanied by a subsequent lower renin protein expression in accordance with the still high blood pressure in the rats." (PMID 30198211, 2018). "However, it did not alter high blood pressure in Renin-Tg mice." (PMID 32905409, 2020). "The development of lung fibrosis depends upon the renin-Ang II-AT1 cascade, but is independent of high blood pressure." (PMID 26494430, 2015). "These genes are believed to control the renin–angiotensin–aldosterone system (RAAS) and the production of neprilysin, which could help protect adults with DS from developing high blood pressure and might explain why they do not experience increased arterial stiffness." (PMID 39311292, 2024).
central obesity (18 papers, 2008 to 2025). "RHF associated with excess body weight and/or central obesity has been explained with several mechanisms, including activation of the renin-angiotensin-aldosterone system." (PMID 29652920, 2018). "Additionally, excess body weight, particularly abdominal obesity, is associated with increased activity of the sympathetic nervous system and the renin–angiotensin–aldosterone system, contributing to increased blood pressure." (PMID 40871625, 2025). "Patients with central obesity are known to have increased activation of the renin–angiotensin–aldosterone system, which may also normalize after surgery." (PMID 37159461, 2023). "In central obesity, activating the renin–angiotensin system may lead to altered hemodynamics." (PMID 36142036, 2022). "Waist circumference (abdominal obesity) is a well‐known cause of LVDD among the components of MetS, which can affect multiple metabolic and neurohormonal pathways due to accumulation of adipose tissue, causing abnormalities in the renin‐angiotensin system and myocardial oxidative stress." (PMID 35502633, 2022). "In abdominal obesity, the levels of RAAS components such as renin, angiotensin, and aldosterone are significantly increased, and the elevated levels of aldosterone exceed the renin activity." (PMID 37386040, 2023).
glomerular disease (18 papers, 2013 to 2025). "In a randomized trial on children with CKD mostly due to CAKUT or glomerulopathies, lowering proteinuria by renin-angiotensin-aldosterone system inhibition has been associated with long-term preservation of kidney function." (PMID 41278353, 2025). "For instance, plasma renin activity has been elevated in human glomerulonephritis and various experimental models of glomerular disease." (PMID 39044930, 2024). "Among these, glomerulopathy, inflammation, dysfunction of the endothelium, activation of the sympathetic nervous system, and renin-angiotensin-aldosterone system (RAAS) are mentioned." (PMID 36644578, 2023). "AKI is related to many factors, including renal interstitial edema, glomerular disease, hypoperfusion, renal tubular epithelial cells necrosis, renin–angiotensin–aldosterone system (RAAS) activation." (PMID 35247980, 2022). "Glomerular diseases including Alport syndrome are primarily treated with renin–angiotensin system (RAS) inhibitors, immunosuppressive agents, and steroids." (PMID 33782421, 2021). "Reducing proteinuria with immune modulating therapy or renin-angiotensin system blockers is the cornerstone of therapy for glomerular diseases." (PMID 27525120, 2016). "Juxtaglomerular cells of the renin lineage have also been described to migrate into the glomerulus and differentiate into podocytes, epithelial cells or mesangial cells to restore damaged cells in states of glomerular disease." (PMID 35511367, 2022). "The prognosis of patients with MPN-related glomerulopathy, unlike those with other glomerulopathies, remains guarded even after corticosteroid therapy, renin-angiotensin system blockade, and treatment of the underlying neoplasm." (PMID 26232031, 2015). "Proteinuria is considered a prognostic factor for progressive renal disease and is the main manifestation of glomerular disease and disability because of alterations in normal permselectivity and increased activation of the renin angiotensin aldosterone system in 5/6Nx." (PMID 23408975, 2013).
Hypervolemia (18 papers, 2014 to 2026). An increase in the amount of intravascular fluid, particularly in the volume of the circulating blood. "Among multiple mechanisms, DOCA-salt-induced hypertension was strongly linked to impaired renin-angiotensin pathway and hypervolemia, in which the kidney reabsorbs excessive sodium and water due to deranged renal sodium handling capacity." (PMID 37055870, 2023). "PA is associated with low plasma renin activity (or concentration) because aldosterone-induced hypervolemia results in suppression of renin release." (PMID 32266384, 2020). "It is characterized by increased aldosterone secretion causing salt retention, increased urinary potassium excretion, relative hypervolemia, suppressed plasma renin activity (PRA), and hypertension." (PMID 27445975, 2016). "The observed hemodynamic response is presumably due to different mechanisms of action, such as secretion of catecholamines and renin-angiotensin, blood volume redistribution with absorption of intestinal fluid into the circulation, and venous capacity reduction inducing central hypervolemia." (PMID 32122358, 2020). "For instance, blood pressure may be elevated after onset of AKI due to renin-angiotensin-aldosterone system activation and/or hypervolemia as a consequence of oliguria." (PMID 25175670, 2014). "Cardiac patients might have more often moderate venous congestion due to chronic disease progression with chronic congestion in the context of neurohormonal alterations (i.e. sympathetic activation, renin–angiotensin–aldosterone system activation, etc.)and hypervolemia." (PMID 37291662, 2023). "Renin and the RAAS components are suppressed when blood volume is normal (normovolemia) or high (hypervolemia), which can occur with excessive intake or impaired excretion of fluids and sodium." (PMID 41349545, 2026). "The etiology of this relative hypervolemia does not appear to correlate with dietary sodium intake, but could be influenced by renin-angiotensin system activation." (PMID 24801204, 2014).
Liddle syndrome (18 papers, 2005 to 2025). A rare genetic form of low-renin hypertension characterized by hypertension associated with decreased plasma levels of potassium and aldosterone. "However, there are other pathologies that can lead to a low-renin condition, as occurs in Liddle syndrome, which is the most common cause of LRH in the African American population." (PMID 38586159, 2024). "This is in contrast to Liddle’s syndrome, where plasma renin and aldosterone activity are markedly suppressed." (PMID 39184766, 2024). "Liddle syndrome (LS) (or pseudoaldosteronism) (OMIM:177200) is an autosomal dominant form of salt-sensitive HTN associated with low plasma aldosterone, low plasma renin activity, hypokalemia and metabolic alkalosis." (PMID 37175488, 2023). "Since low plasma renin activity and a low aldosterone level were also found, the patient was diagnosed with pseudoaldosteronism due to licorice." (PMID 30733510, 2019). "The differential diagnosis of hypokalemic hypertension with low renin includes mineralocorticoid excess, with the mineralocorticoid being cortisol or 11-deoxycorticosterone, apparent mineralocorticoid excess, pseudo-hypermineralocorticoidism in Liddle syndrome or exposure to glycyrrhizic acid." (PMID 20482833, 2010).
rheumatoid arthritis (18 papers, 2015 to 2026). A chronic, systemic autoimmune disorder characterized by inflammation in the synovial membranes and articular surfaces. "Lastly, KEGG pathway analysis (p < 0.01, FDR < 0.05) indicated that the DEGs were enriched in pathways associated with the renin–angiotensin system; complement and coagulation cascades; and those related to diseases like malaria, rheumatoid arthritis, and diabetic complications." (PMID 40361912, 2025). "The Renin-Angiotensin-Aldosterone system (RAAS) has been implicated in the regulation of the cardiovascular system and linked to rheumatoid arthritis (RA)." (PMID 37877017, 2023). "Rheumatoid arthritis (RA) is an autoimmune inflammatory bone destructive disorder that is orchestrated by multiple systems in the body, including Renin-Angiotensin System (RAS) and arachidonic acid (ArA) pathway." (PMID 36015308, 2022). "The overexpression of both Dkk1 and Bmi1 was found to be related to cytokine‐cytokine receptor interactions, rheumatoid arthritis, renin secretion, and nitrogen metabolism in our study." (PMID 33639034, 2021). "Only two pathways were common to the ILLN and JELN (Renin-angiotensin system and Rheumatoid arthritis pathways)." (PMID 34975852, 2021). "Three (IL-17 signaling pathway, Malaria and Renin-angiotensin system) out of seven ILLN KEGG pathways were enriched with down-regulated genes while the other four (NF-κB signaling pathway, Mineral absorption, Melanoma and Rheumatoid arthritis) were enriched with both up- and down-regulated genes." (PMID 34975852, 2021).